DNMT1 (DNA methyltransferase 1)
Diseases named in the same sentence as DNMT1 in open-access papers (continued):
Sharing a sentence is not in itself a finding about the gene and the disease.
breast cancer (continued). "Approximately, 30% of breast cancer patients showed overexpression of DNMT3B and 3–5% showed overexpression of DNMT1 and DNMT3A." (PMID 33604794, 2021). "In summary, our findings demonstrate that the expression of DNMT1 and the methylation level of KLF4 promoter increased, while the expression of KLF4 decreased in breast cancer tissues." (PMID 34150611, 2021). "The role of miR-185 has been investigated in various cancers including lung cancer, osteosarcoma and breast cancer by targeting SOX9, HK2, DNMT1 and E2F6, respectively." (PMID 33507687, 2021). "The DNMT1 and DNMT3A expression levels were significantly higher in breast cancer than in fibroadenoma samples." (PMID 33498667, 2021). "The results showed that the expression of DNMT1 was lower in breast normal tissues with relatively high KLF4 expression, while DNMT1 was significantly increased in breast cancer tissues with relatively low KLF4 expression." (PMID 34150611, 2021). "DIM can effectively decrease the expression of DNMT1 and the methylation level of KLF4 in breast cancer cells, and then promote the expression of KLF4." (PMID 34150611, 2021). "Here, we demonstrated that DNMT1 promoted the methylation of KLF4 promoter and thus decreased KLF4 expression, which was correlated with the PTX sensitivity in breast cancer." (PMID 34150611, 2021). "In another study, the expression of DNMT1, DNMT3A, and DNMT3B in 256 breast cancer and 36 breast fibroadenoma cases were investigated." (PMID 33498667, 2021). "Similar results were obtained in human breast cancer cell lines (MCF-7 and MDA-MB-231), whereas EGCG was able to block prokaryotic SssI DNA methyltransferase (DNMT) and human DNMT1." (PMID 31979082, 2020). "Earlier we demonstrated a concentration and time-dependent down-regulation of DNMT1 in cell lines with various histological backgrounds (NSCLC, ovarian cancer, pancreatic cancer, breast cancer)." (PMID 32295203, 2020). "Collectively, our findings suggest an important role of the DNMT1/FOXO3a/FOXM1/SOX2 pathway in regulating BCSCs properties, suggesting potential therapeutic targets for breast cancer." (PMID 31296961, 2020). "In this context, resveratrol demonstrated an ability to suppress enzymatic activity of DNMT and also mRNA levels of DNMT1, DNMT3A and DNMT3B in HCC1806 breast cancer cells." (PMID 32397145, 2020). "In breast cancer cell lines, resveratrol inhibits both HDAC and DNMT1 activity, decreases histone H3 lysine 27 methylation, and increases its acetylation." (PMID 33312959, 2020). "In a breast cancer cell model, this compound inhibited HDAC and DNMT1 activity, decreasing histone H3 lysine 27 methylation and increasing its acetylation status." (PMID 32365701, 2020). "In breast cancer (MCF-7 and MDA-MB-231) cell lines, genistein (60 and 100 μM) was shown to decrease global DNA methylation by inhibiting DNMT activity and DNMT1 expression." (PMID 32878338, 2020). "It is noted that DNMT1, DNMT3a, and DNMT3b are all recruited to the FOXO3 promoter in breast cancer HCC70 and MDA-MB-468 cells." (PMID 31296961, 2020). "In mammary gland and breast carcinoma, ZEB1 inhibits CDH1 expression by interacting with DNA methyltransferase 1 (DNMT1)." (PMID 32796736, 2020). "The dietary chalcone isoliquiritigenin, which is found mainly in licorice root, significantly inhibited breast cancer progression via the demethylation of the WIF1 promoter region, which correlated with the inhibition of DNMT1 in a xenograft mouse model." (PMID 31323834, 2019). "For instance, curcumin inhibited DNMT1 expression and restored the function of RASSF1A by promoter hypomethylation in estrogen positive MCF-7 breast cancer cell line." (PMID 30881375, 2019). "DNMT1 inhibitors, ChIP, CoIP, IHC and ERα inhibitors were used to explore the molecular mechanism of OCT4 in breast cancer." (PMID 31012189, 2019).
breast cancer (continued). "Inactivation of the TGFβ/SMAD pathway has been shown to inhibit cell invasion by suppressing DNMT1 and claudin-6 methylation and expression in MCF-7 and SKBR-3 breast cancer cell lines." (PMID 31717460, 2019). "Another recent study demonstrated that thymoquinone can decrease the expression of some important epigenetic proteins like DNMT1,3A,3B and HDAC1 in Jurkat cells and breast cancer cells." (PMID 31878334, 2019). "DNMT1 promotes hypermethylation and downregulation of tumor suppressor gene ISL1 which increases the tumor stem cell population in breast cancer cells." (PMID 31828117, 2019). "Down-regulation of DNMT1 was also described in melanoma cells and MCF-7 breast cancer cells after treatment with curcumin, a natural phenol." (PMID 30171426, 2018). "Our data reveal a novel axis of miR-506/SP3/SP1/DNMT1/MEG3 in regulating migration and invasion of breast cancer cell lines, which provide rationales for developing effective therapies to treating metastatic breast cancers." (PMID 30386180, 2018). "Consistent with the role of DNMT1 in maintaining MaSCs, it is also required for cancer stem cell (CSC) maintenance in the MMTV-Neu-Tg mouse mammary tumour model of HER2+ breast cancer." (PMID 30176939, 2018). "The Snail-G9a-Dnmt1 complex, which is critical for E-cadherin promoter silencing, was also responsible for the promoter methylation of FBP1 in basal-like breast cancer cells." (PMID 30429463, 2018). "Our data demonstrated that, in breast cancer cells, the low expression of CLDN6 was regulated by DNMT1 mediated methylation, which was in turn regulated by the SMAD2 pathway." (PMID 28867761, 2017). "Therefore, DNMT1 might have diverse functions in different types of breast cancer." (PMID 28473984, 2017). "Further study indicated that TET1 siRNA and pcDNA3/Myc-DNMT1 inhibited the 3,6-DHF reactivation effect on expression of miR-34a in breast cancer cells." (PMID 28870206, 2017). "Regarding the importance of DNMT3b, several studies demonstrated that DNMT3b is overexpressed at higher frequency than DNMT3a and DNMT1 in CRC and breast cancer 27–29." (PMID 28090275, 2017). "In conclusion, SMAD2 downregulated CLDN6 via DNMT1 mediated DNA methylation to promote EMT, thereby accelerating the migration and invasion of breast cancer cells." (PMID 28867761, 2017). "To further analyze DNMTs and HDACs we assessed key epigenetic modifiers, DNMT1, DNMT3A, DNMT3B and HDAC1, and found decreases at both the mRNA and protein levels in one or both breast cancer cell lines." (PMID 28534825, 2017). "Tollefsbol and coworkers reported that 15 μM RVT was able to decrease DNMT enzymatic activity and mRNA levels of DNMT1, DNMT3A and DNMT3B in HCC1806 breast cancer cells." (PMID 29104258, 2017). "In another study, Romagnolo and coworkers used MCF-7 breast cancer cells and reported that RVT was able to reduce DNMT1 activity at the BRCA-1 promoter." (PMID 29104258, 2017). "Consistently, the DNMT1 expression was positively correlated with ERα expression in breast cancer tissues and negatively correlated with RFS and DMFS of ERα-positive breast cancer patients." (PMID 26980709, 2016). "Our data demonstrated that anticancer drug paclitaxel (PTX) augmented ERα binding to the DNMT1 and DNMT3b promoters to activate DNMT1 and DNMT3b genes, enhancing the PTX resistance of breast cancer cells." (PMID 26980709, 2016). "We assessed the expression of methylation-related proteins 5-meC, DNMT1, and ISL-1 in breast cancer and evaluated their relationship to clinicopathological factors." (PMID 27071379, 2016). "We assessed the expression of methylation-related proteins 5-meC, DNMT1, and ISL-1 in breast cancer and evaluated their relationships with clinicopathological factors." (PMID 27071379, 2016). "The Kaplan-Meier Plotter analysis indicates that DNMT1 expression was negatively correlated with RFS and DMFS of ERα-positive breast cancer patients." (PMID 26980709, 2016).
breast cancer (continued). "Patients with high DNMT1 expression in their breast cancer samples had lower relapse-free survival (RFS) and distance metastasis-free survival (DMFS) than those with low DNMT1 expression in the samples." (PMID 26980709, 2016). "miR-185 suppresses tumor proliferation in breast cancer by directly targeting E2F6 and DNMT1 and indirectly up-regulating BRCA139." (PMID 27686215, 2016). "Immunohistochemical staining for ER, PR, HER-2, Ki-67, 5-meC, DNMT1, and ISL-1 were performed on 348 breast cancer samples in tissue microarray." (PMID 27071379, 2016). "These two dietary polyphenols when administered (72 h) in HCC1806 breast cancer cells resulted in down-regulation of DNMT1, 3A and 3B at the gene level as well as at the enzymatic activity level in HCC1806 breast cancer cells." (PMID 26459286, 2015). "In addition, we analyzed the correlation between DNMT1-positive cells or mRNA levels and the number of methylated sites within the E2F1 motif (+182) or DNMT1 core promoter region (-99 to +521) in BRCA1-mutated breast cancer and adjacent normal breast tissue (Figure2Ei-Eiv)." (PMID 24502362, 2014). "In fact, it has been observed that DNMT1 and E2F3 are candidate targets of miR-152 in HCC, endometrial and breast cancer; BTRC has been shown to ubiquitinate phosphorylated NFKBIA, targeting it for degradation and thus activating NF-κB." (PMID 25330074, 2014). "In MCF-7 and MDA-MB-231 breast cancer cells, high concentrations of GEN (60, 100 μM) dose- and time-dependently reduced DNMT1 mRNA and protein expression and DNMT activity." (PMID 25322458, 2014). "In terms of biologic results, our data show that the breast cancer cell lines (MDA-MD-231 and Cal-51) harbored less Dnmt1/PCNA interactions and less 5-methycytosine (5 mC) than non-tumor breast cells (MCF10A)." (PMID 21470401, 2011). "Recent studies also showed combination therapy involving HDAC inhibitors with DNA methyltransferase-1 (DNMT1) inhibition is synergistically effective in inducing apoptosis, differentiation and/or cell growth arrest in many cancers including breast cancer." (PMID 21814622, 2011). "RNAi-mediated knockdown of DNMT1 resulted in significant reduction of promoter methylation and re-expression of RASSF1A, p16, and HPP1 in HCC1954 breast cancer cells." (PMID 21999220, 2011). "In breast cancer, silencing of RASSF1A is commonly attributed to DNA methylation, yet whether this process is directly regulated by DNMT1—and how this regulation contributes to brain metastasis—remains to be elucidated." (PMID 41381440, 2025). "Besides, FOXO3a can be hypermethylated by DNA (cytosine-5-)-methyltransferase 1 (DNMT1) and resulted in its downregulation, which led to the promotion of breast cancer stem cell properties and tumorigenesis." (PMID 39991565, 2025). "First, this study did not include breast cancer brain metastasis patient samples with detailed clinical outcomes such as OS or metastasis-free survival, limiting direct prognostic evaluation of DNMT1 and RASSF1A." (PMID 41381440, 2025). "Collectively, these findings provide evidence that targeting DNMT1 and HDAC1 enhances the expression of PD-L1, and the concurrent administration of an anti-PD-L1 agent represents a novel approach for the treatment of breast cancer." (PMID 38490978, 2024). "First, we investigated DNMT1 and HDAC1 expression in normal and breast cancer subtypes." (PMID 38490978, 2024). "In the present study, we investigated the possibility that TQ would show similar inhibitory effects in vitro on the MCF7 and T47D human breast cancer cell lines and in vivo in a rat model of 7,12-dimethylbenzanthracene (DMBA)-induced BC through its ability to modulate DNMT1 expression." (PMID 38257347, 2024). "In addition, higher expression of DNMT1 and DNMT3A was found in TNBC than in other breast cancer subtypes." (PMID 36982660, 2023).
breast cancer (continued). "This study emphasized specific role of epigenetic modifiers like DNMT1 and HDAC1 & HDAC2 on proliferation and apoptosis, as well as aggressiveness, invasion and metastasis in terms of EMT through centrosome amplification in breast cancer." (PMID 36774386, 2023). "In addition, overexpression of DNMT1 was observed in TNBC and HER2+ subtypes that validates its oncogenic roles in breast cancer and drug target of TNBC." (PMID 36788602, 2023). "Interestingly, in a cohort of 100 tumors from locally advanced breast cancer patients (LABC), we have shown that high expression of DNMT1 in tumor cells and their adjacent stromal fibroblasts is correlated with poor survival of these patients." (PMID 35719957, 2022). "Finally, to evaluate the clinical significance of our findings, we performed immunohistochemistry (IHC) staining of breast cancer tissue microarray slides (TMAs) using anti-CD163 (TAM marker), anti-ZEB1 and anti-DNMT1 antibodies." (PMID 36273188, 2022). "DNMT1, DNMT3A and DNMT3B increased the DNA methylation of FOXF2 in breast cancer cells." (PMID 35620052, 2022). "Additionally, 5-azadC suppresses the expression of DNMT1, IGF4, and ERRα (NR3B1) and mitigates breast cancer progression." (PMID 35453496, 2022). "Similarly, overexpression of miR-29b-1-5p repressed the expression of DNMT1, DNMT3A and DNMT3B and elevated the expression of RASSF1A, CCND2 and HIN1 in breast cancer cells." (PMID 35620052, 2022). "However, after PAS1 was suppressed by DNMT1 overexpression, PH20 expression was activated, which subsequently promoted breast cancer progression." (PMID 35307730, 2022). "The hypermethylation in the CXCL12 promoter region in more than 50% of breast tumors was detected by methylation-specific PCR, and the expressions of DNMT1 and DNMT3b were distinctly higher in CXCL12-methylated breast cancers than in CXCL12-unmethylated breast cancers." (PMID 35770088, 2022). "The obtained findings of our work revealed that DNMT1 may inhibit miR-497 expression and boost expression of GPRC5A through DNA methylation, thus augmenting chemotherapy resistance and metastasis in breast cancer." (PMID 35255904, 2022). "DNMT1 can induce the EMT program and facilitate cell motility in breast cancer." (PMID 36273188, 2022). "Firstly, DNMT1 was highly-expressed and miR-497 was poorly-expressed in breast cancer, whilst exhibiting negative-correlation." (PMID 35255904, 2022). "As our results showed, the migration and invasion abilities were elevated when DNMT1 was overexpressed in nonmetastatic MCF7 breast cancer cells." (PMID 36273188, 2022). "In addition, we also studied the methylation status of MEG3 promoter after DNMT1 silencing and the role of MEG3 on breast cancer growth in vivo." (PMID 35109842, 2022). "Real-time PCR and Western blotting analysis revealed that DIM could significantly decrease the DNMT1 expression and increase the KLF4 expression in MCF-7 and T47D breast cancer cells." (PMID 34150611, 2021). "Furthermore, after knockdown DNMT1 expression in MCF-7 and T47D breast cancer cells, the expression of KLF4 increased, and the sensitivity of breast cancer cells to PTX significantly increased." (PMID 34150611, 2021). "Although deletion of p18 stimulates expression of DNMT1 in MECs and stromal cells, mice lacking p18 develop Gata3-positive well-differentiated mammary tumors." (PMID 34373738, 2021). "Our data showed that the expression of DNMT1 was increased, and the methylation level of CpG sites (−148 bp) in the KLF4 promoter was increased while the KLF4 expression was significantly decreased in breast cancer tissues." (PMID 34150611, 2021). "As DMAP1 is also named Dnmt1-associated protein 1, and it has a binding role and a potent activation role in DNMT1 methylation, we speculate that DMAP1 may control the biological properties of breast cancer through its gene methylation ability." (PMID 34834420, 2021).
breast cancer (continued). "Therefore, a drug that can inhibit DNMT1 expression and promote the expression of KLF4 would considerably improve the status of PTX resistance in the clinical treatment of breast cancer." (PMID 34150611, 2021). "Thus, TSA treatment was shown to cause genomic hypomethylation as a result of decreased nuclear DNMT1 levels in T24 cells (bladder carcinoma) and also in MDA-MB-231 cells (breast carcinoma)." (PMID 34066975, 2021). "A decrease in DNMT1 expression by resveratrol (14 μM; 72 h) was also accompanied with a decreased PTEN promoter methylation and increased PTEN expression levels in the MCF7 breast cancer cell line." (PMID 32878338, 2020). "Similarly, resveratrol was shown to inhibit DNMT1 activity and expression at the BRCA1 promoter, leading to promoter hypomethylation and the reactivation of BRCA1 in breast cancer cells." (PMID 32878338, 2020). "STAT3 also mediates oncogenesis by recruiting DNA methyltransferase 1 (DNMT1) to gene promoters to silence tumours suppressor genes, such as PTPN6, IL-2Rγ, CDKN2A, DLEC1, and STAT1 by CpG methylation in malignant T lymphocytes and breast cancer cells." (PMID 33086505, 2020). "Circular RNA FLI1, circKIF4A, circRAD18, circ-DNMT1 and circPLK1 were also identified as oncogenic drivers by different mechanisms (maintaining DNA methylation, promoting EMT, reducing apoptosis or activating autophagy) in breast cancer." (PMID 32756009, 2020). "Resveratrol (15 μM) was shown to decrease the enzymatic activity and mRNA expression levels of DNMT1, DNMT3A, and DNMT3B in MDA-MB-157 and HCC1806 breast cancer cell lines, which led to a significant decrease in 5-methylcytosine levels and an overall reduction in global DNA methylation patterns." (PMID 32878338, 2020). "Prior to VPA/hydralazine treatment, DNMT3a, DNMT1 or HDAC1 expression was not different in the mammary tumors of HF offspring, compared with controls." (PMID 31889127, 2019). "By detecting DNMT1, DNMT3A, and DNMT3B mRNA levels, as well as DNMT3A protein levels in MAML1-overexpressing breast cancer cells, we confirmed that MAML1 could up-regulate DNMT3A expression." (PMID 31660998, 2019). "Moreover, dietary isoflavone genistein was proposed as an antagonist of DNMT1 in MCF7 and MDA-MB-231 breast cancer cell lines." (PMID 31323834, 2019). "Additionally, MPPED2-AS1 was also found downregulated in breast cancer tissues and, intriguingly, its expression decreased the hypermethylation of the MPPED2 promoter by inhibiting DNA methyltransferase 1 (DNMT1)." (PMID 31181813, 2019). "Elevated SIRT1 deacetylase modulate the nuclear localization of FOXO1, an apoptosis associated EMT-TF and deacetylate the acetylated DNMT1 thus inhibition of SIRT1 enhance the DNMT1-mediated silencing of ER-α and CDH1 reflecting mesenchymal acquisition in MDA-MB-231 breast cancer cells." (PMID 35582717, 2019). "To explore which type of DNA methyltransferases could be affected by MAML1, we first analyzed the correlation between MAML1 and common DNA methyltransferases (DNMT1, DNMT3A/B) in 1085 breast cancer tissues from the GEPIA public database." (PMID 31660998, 2019). "STAT3 also mediates oncogenesis by recruiting DNA methyltransferase 1 (DNMT1) to gene promoters to silence tumor suppressor genes, such as PTPN6, IL-2Rγ, CDKN2A, DLEC1, and STAT1 by CpG methylation in malignant T lymphocytes and breast cancer cells." (PMID 29728695, 2018). "After treating the two breast cancer cell lines with SB431542, a TGFβ type I receptor inhibitor that specifically inhibits SMAD2 and SMAD3 phosphorylation, which leads to down regulation of DNMT1 and upregulation of CLDN6." (PMID 28867761, 2017). "Thus, CLDN6 is the key regulator in the SMAD2/DNMT1/CLDN6 pathway to inhibit EMT and migration and invasion of breast cancer cells." (PMID 28867761, 2017).